PIR (pirin)
Diseases named in the same sentence as PIR in open-access papers (continued):
Sharing a sentence is not in itself a finding about the gene and the disease.
gastric cancer (14 papers, 2013 to 2026). A primary or metastatic malignant neoplasm involving the stomach. "piR‐hsa‐1282 dysregulation associated with gastric cancer was validated by RT‐PCR and the animal model experiments in vivo." (PMID 39228010, 2024). "Individuals suffering from gastric cancer exhibit notable amounts of PiR-1245 in their gastric juices." (PMID 40296904, 2025). "Differential expressions of piR-651, piR-823, piR-932 were reported in cancers of lung, breast, colorectal, esophageal, and gastric cancer." (PMID 37568568, 2023). "It has been also suggested that gastric cancer patients from healthy controls can be detected, by way of measuring the levels of piR-823 and piR-651 in peripheral blood, making possible an early diagnosis of gastric cancer." (PMID 30705933, 2019). "Blood levels of piR-823 in gastric cancer patients were significantly lower than in those from healthy controls." (PMID 26379360, 2015). "The levels of piR-823 were positively associated with TNM stages and distant metastasis, suggesting that piR-823 should be tested as a biomarker for detecting circulating gastric cancer cells in the blood." (PMID 23965974, 2013). "Another study demonstrated the down-regulation of piR-823 in gastric cancer tissues compared to normal tissues suggesting its potential tumor suppressive role." (PMID 23965974, 2013). "The study found that the expression of piR-019308, piR-004918, and piR-018569 in the serum exosomes of gastric cancer patients was significantly higher than that of normal people, and the expression levels of piR-004918 and piR-019308 were related to metastasis." (PMID 40296904, 2025). "Further functional studies indicated that restoration of piR-823 expression in gastric cancer cell lines inhibited tumor cell growth by 40% in vitro and 75% in vivo and inhibition of over-expressed piR-651 with antisense oligos resulted in a 30% reduction in tumor growth rate." (PMID 30701019, 2018). "As already mentioned, piR-30924 was found to be upregulated in gastric cancer." (PMID 26071182, 2015). "In contrast, expression levels of piR-823 were significantly underexpressed in human gastric cancer tissue samples when compared with paired noncancerous tissues." (PMID 26379360, 2015).
pancreatic cancer (12 papers, 2016 to 2025). "Sequencing analysis showed that piRNAs including hsa-piR-52959, hsa-piR-53108, hsa-piR-30690, hsa-piR-54479, and hsa-piR-56621 were up-regulated in patients with pancreatic cancer compared to healthy people, suggesting the oncogenic effects of these piRNA." (PMID 34439315, 2021). "The same study also found that the following piRNAs are upregulated in pancreatic cancer: hsa-piR-52959, hsa-piR-53108, hsa-piR-30690, hsa-piR-54479, hsa-piR-56621, hsa-piR-54888, hsa-piR-42185, hsa-piR-46410, hsa-piR-58897, hsa-piR-58897." (PMID 32824183, 2020). "PiR-017061 arrests pancreatic cancer growth by down-regulating EFNA5 expression." (PMID 40606680, 2025). "Interestingly, piR-162725 expression identified pancreatic cancer patients versus healthy donors in liquid biopsies." (PMID 36555927, 2022). "Whereas, several piRNAs such as hsa-piR-54888, hsa-piR-42185, hsa-piR-46410, hsa-piR-58897, and hsa-piR-43043 were down-regulated in patients with pancreatic cancer, suggesting that these piRNAs could have tumor suppressive functions." (PMID 34439315, 2021). "These two findings indicate that piR-162725 could play an oncogenic role in pancreatic cancer." (PMID 36555927, 2022). "Additional regulators such as pirin (PIR) exert similar control, as PIR depletion enhances HMGB1 cytosolic translocation and activates Beclin1-ACSL4 autophagic machinery to potentiate ferroptosis in pancreatic cancer." (PMID 41465435, 2025). "By regulating PIR expression, MCP exerts dual biological effects: it induces ferroptosis in pancreatic cancer cells by suppressing GPX4 and promotes macrophage pro‐inflammatory M1‐like polarization by enhancing cytoplasmic translocation and the early release of HMGB1." (PMID 38593415, 2024). "Pir, the full name is Pirin, is a nonheme iron (Fe) binding nuclear protein, plays an important role in mediating ferroptosis resistance in human pancreatic cancer cells." (PMID 37576602, 2023). "Additionally, Pirin has been shown to play role in resistance to ferroptosis, which is an iron-dependent non-apoptotic cell death, in human pancreatic cancer cells." (PMID 38033031, 2023). "Furthermore, the iron-binding nuclear protein pirin (PIR) can hijack HMGB1 in the nucleus, thereby inhibiting the translocation of HMGB1 to the cytoplasm and subsequent activation of beclin 1 (BECN1)-dependent autophagy and ferroptosis in pancreatic cancer cells." (PMID 36845736, 2023).
cervical carcinoma (7 papers, 2017 to 2024). A carcinoma arising from either the exocervical squamous epithelium or the endocervical glandular epithelium. "Taken together, our results show that HPV-16 E6/E7 induce pirin expression in oral and cervical cancer cells and that this effect is associated with the expression of EMT markers." (PMID 29118270, 2017). "Another study indicated that CUR decreased the EMT through a Pirin-dependent mechanism in cervical cancer cells." (PMID 39202273, 2024). "We demonstrated for the first time that Pirin is expressed in a HPV load-dependent manner in cervical cancer cells." (PMID 33557375, 2021). "This is the first study reporting HR-HPV-dependent PIR upregulation in oral and cervical cancer cells." (PMID 29118270, 2017). "Considering the results obtained in this study, it is plausible that an increase in DNA damage and activation of the DNA damage response (DDR) in the presence of HR-HPV is related to pirin increase in oral or cervical cancer cells." (PMID 29118270, 2017). "In this study, we found that pirin, the product of the PIR gene and an oxidative stress sensor, is consistently overexpressed in HR-HPV-associated tumours including head and neck and cervical cancer cells." (PMID 29118270, 2017). "In oral and cervical cells, PIR gene silencing with small interfering RNA (siRNA) was shown to increase E-cadherin transcripts as well as reduce Vimentin, Slug, Zeb and Snail transcripts in oral and cervical cancer cells." (PMID 38033031, 2023). "However, C33A, an HPV-negative cervical cancer cell line, exhibited almost undetectable levels of pirin." (PMID 29118270, 2017). "Finally, we found that HR-HPV-associated PIR overexpression is related to increased migration and epithelial–mesenchymal transition (EMT) properties of oral and cervical cancer cells expressing HR-HPV E6 and E7." (PMID 29118270, 2017). "The potential value of pirin expression as a surrogate biomarker of HR-HPV in head and neck or cervical cancer warrants additional investigation." (PMID 29118270, 2017). "Taken together, these results clearly showed that pirin overexpression is at least dependent on ectopic or endogenous HPV-16 E6 and E7 expression in oral and cervical cancer cells." (PMID 29118270, 2017). "Next, a dose–response effect was analysed using C4I cervical cancer cells, which are HPV-18 positive although with low levels of pirin expression." (PMID 29118270, 2017). "Notably, we demonstrated that curcumin decreases Pirin levels and reduces EMT and cell migration, suggesting a novel Pirin-dependent mechanism wherein curcumin rescues cervical cancer cells from EMT." (PMID 33557375, 2021). "Considering that Pirin is a NF-κB activator, we hypothesize that Pirin may act as a mediator between NRF2 and NF-κB in cervical cancer cells." (PMID 33557375, 2021). "Pirin can also mediate metastasis of cervical cancer cells independent of BCL3-SNAI2 signaling." (PMID 38033031, 2023). "Additionally, it was demonstrated that PIR knockdown increases E-cadherin levels and reduces Slug, zinc finger E-box-binding homeobox protein (ZEB) and Snail in cervical cancer cells, suggesting its contribution to epithelial–mesenchymal transition (EMT) and cell migration." (PMID 33557375, 2021). "However, PIR upregulation is not observed in HR-HPV-negative cervical cancer-derived cell lines." (PMID 29118270, 2017). "Interestingly, we found that Pirin levels are increased by HPV16 E6 and E7 oncoproteins in infected cervical cancer cells, unlike HPV-negative cells." (PMID 33557375, 2021). "Likewise, E7 involvement in PI3K/AKT1 activation and was relevant during the progression of cervical cancer, while, regarding the EGF pathway, Gefitinib incubation did not alter Pirin levels." (PMID 32679705, 2020).
glioma (7 papers, 2016 to 2024). A benign or malignant brain and spinal cord tumor that arises from glial cells (astrocytes, oligodendrocytes, ependymal cells). "piR-598 functional analysis showed that wild-type piRNA transfection affected the expression of genes implicated in cell death and survival, and attenuated colony formation and glioma cell viability." (PMID 33109195, 2020). "Use of genetic association analysis has identified numerous piRNAs related to glioma risk, and follow-up functional analysis suggested that variant rs147061479 in piR-598 increased glioma risk by abolishing the tumor-inhibitory property of piR-598, and instead conferring growth-promoting properties." (PMID 33109195, 2020). "Also, several other groups have reported the aberrant expression of piR-DQ590027, piR-DQ593109 and piR-30188 in human glioma tissues and cell lines." (PMID 38059120, 2024). "Up-regulation of miR-367-3p, piR-30,188 and PIWIL3 or knockdown of OIP5-AS1 led to suppression of glioma progression." (PMID 33109195, 2020). "PIWIL3 plus piR-30,188 and the PIWIL3/OIP5-AS1/miR-367-3p/CEBPA (CCAAT/enhancer-binding protein alpha) complex is involved in the pathogenesis of glioma." (PMID 33109195, 2020). "It encodes for the iron-binding nuclear protein pirin, a transcriptional regulator, and has been described as an oncogene and promoter of metastatic tumor growth on one hand and as a tumor suppressor gene on the other in many solid cancers, but never before in glioma." (PMID 27782828, 2016). "Thereafter, a recent study showed that piR-30188 could regulate the expression of CEBPA by targeting lncRNA OIP5-AS1 at the post-transcriptional level, thus inhibiting the proliferation of glioma cells." (PMID 34803507, 2021). "To test whether piR-8041 affects glioma cell growth in vivo, we implanted luciferase-expressing U87 cells transfected with piR-8041 or negative control RNA intracranially in nude mice." (PMID 30701019, 2018).
prostate carcinoma (6 papers, 2016 to 2024). A carcinoma that arises from epithelial cells of the prostate gland. "PIWIL2 has also been found to be involved in the effects of the overexpression of piR-4447944 in prostate cancer cells." (PMID 39596284, 2024). "The study demonstrated that piR-4447944 plays a critical role in promoting androgen-independent growth in prostate cancer by interacting with PIWIL2." (PMID 39596284, 2024). "PIWI and piRNA are closely related to cancer, but there are few studies on the mechanism of piR-19166 regulating development and progression of prostate cancer." (PMID 32881713, 2020). "Downregulation of piR-001773 and piR-017184 significantly inhibited the growth of prostate cancer and may be therapeutic targets for prostate cancer." (PMID 37941038, 2023). "But the effect of piR-19166 in prostate carcinoma remains unclear." (PMID 32881713, 2020).
acute myeloid leukemia (5 papers, 2010 to 2022). Acute myeloid leukemia (AML) is a group of neoplasms arising from precursor cells committed to the myeloid cell-line differentiation. "We previously found that PIR mRNA expression is silenced by the acute myeloid leukemia (AML)-associated fusion proteins PML/RARα and AML1/ETO both in cellular models and in primary blasts form AML patients." (PMID 20089166, 2010). "In acute myeloid leukemia (AML), PIR was linked to terminal differentiation of myeloid precursors with a downregulation of PIR possibly related to the differentiation arrest observed in AML." (PMID 27782828, 2016). "For example, terminal myeloid differentiation is impaired by down-regulation of PIR, and reduction in pirin activity may be involved in differentiation arrest characteristic of acute myeloid leukemia (AML)." (PMID 35967515, 2022).
hepatocellular carcinoma (5 papers, 2021 to 2026). A malignant tumor that arises from hepatocytes. "A previous study reported that the upregulation of piR-Hep in hepatocellular carcinoma could promote hepatocellular cell proliferation via binding with PIWI2/HILI to affect PI3K/AKT signaling." (PMID 34790278, 2021). "In hepatocellular carcinoma (HCC), a new piRNA, piR-Hep1 has been identified; it is upregulated in HCC with respect to non-tumoral liver cells." (PMID 37568728, 2023).
lymph node metastasis (5 papers, 2013 to 2023). "The higher expression of PIR was significantly associated with presence of lymph node metastasis, suggesting that the expression of PIR is associated with invasiveness and supports the reported association of PIR expression with enhanced malignant potential." (PMID 23374458, 2013). "In addition, we have also demonstrated an association between elevated levels of FAAH and PIR and high number of axillary lymph node involvement and lymph node metastasis, respectively." (PMID 23374458, 2013). "We detected highly significant levels of serum piR-823 expression associated with advanced clinical stages of CRC (III and IV) (7.5± 1.5) (p < 0.001), poor differentiation (9.2 ± 1.9) (p < 0.001), and lymph node metastasis (6.8 ± 2.4) (p < 0.05)." (PMID 33921704, 2021). "However, elevated protein levels of FAAH were positively associated with high number of lymph node involvement and upregulated levels of PIR were positively related with lymph node metastasis." (PMID 23374458, 2013). "The expression of PIR was positively correlated with lymph node metastasis (P = 0.034)." (PMID 23374458, 2013). "Finally, we correlated the piR-hsa-164586 of extracellular vesicles with the clinical characteristics of patients with NSCLC, such as age, gender, pathological subtype of cancer, lymph node metastasis, TNM staging of tumor, and smoking." (PMID 36249068, 2022). "The expression of piR-hsa-164586 was significantly upregulated in stage I without lymph node metastasis." (PMID 36249068, 2022).
metastatic tumors (5 papers, 2015 to 2023). "In contrast, piR-30,924 and piR-38,756 are highly expressed in primary metastatic tumors and have decreased expression in non-metastatic tumors compared to normal tissue." (PMID 38031146, 2023). "piR-57,125 was reported to be down-regulated in ccRCC, especially in metastatic tumors, implying a plausible role of piR-57,125 as a tumor suppressor by inhibiting tumor metastasis." (PMID 38031146, 2023). "In metastatic and non-metastatic clear cell renal cell cancer (ccRCC), piR-30924 and piR-38756 were more highly expressed in metastatic tumors, while piR-57125 was less expressed in metastatic tumors." (PMID 36212439, 2022). "piR-57,125, piR-30,924, and piR-38,756 are potential prognostic biomarkers of ccRCC because the high expression of piR-30,924 and piR-38,756 and low expression of piR-57,125 significantly correlates with the metastatic tumors and bone metastasis." (PMID 38031146, 2023). "Similarly, in vitro suggested that piR-19166 could block cell metastasis of PCa cells and decrease the number of metastatic tumors in lung of nude mice." (PMID 32881713, 2020). "The uniformly reduced expression of piR-57125 in the sequence from the non-malignant tissue over the primary non-metastatic and primary metastatic tumor to the distant metastases contrasted with the differently regulated expression of piR-30924 and piR-38756." (PMID 26071182, 2015). "piR-57125 showed lower expression in metastatic than in non-metastatic tumors, whereas the expression of piR-30924 and piR-38756 increased in metastatic tumors." (PMID 26071182, 2015). "The higher expression of piR-30924 and piR-38756 as well as the lower expression of piR-57125 in metastatic tumors and bone metastases compared to the non-metastatic primary tumors was significantly associated with the two clinical endpoints." (PMID 26071182, 2015).
ovarian carcinoma (5 papers, 2020 to 2025). A malignant neoplasm originating from the surface ovarian epithelium. "For example, piR-009295 is associated with epithelial–mesenchymal transition (EMT) processes in ovarian cancer, suggesting a role in tumor progression." (PMID 40004152, 2025). "Therefore, we delved into piRNAs that are lowly expressed in ovarian cancer and found piR-26441, which is located on chromosome 14." (PMID 39827178, 2025). "Thus, piR-52207 and piR-33733 promote ovarian cancer oncogenes via involvement in multiple cell-signaling pathways at the post-transcriptional level, supporting them as possible therapeutic targets for ovarian cancer." (PMID 33802524, 2021). "Subsequently, pirin was identified as a high affinity molecular target of bisamide (CCT251236) and shown to decrease tumour growth in a human ovarian carcinoma xenograft model." (PMID 35204145, 2022).
viral infections (4 papers, 2023 to 2026). "Similarly, piR-33036 target includes miRNA-30e-5p that was reported to have a critical role in innate immune responses during viral infections." (PMID 40573354, 2025). "Remarkably, piR-bmo-796514 exhibited a significant upregulation in the silkworm fat body after BmNPV infection at 24 hours post-infection (hpi), suggesting that it may play a role in the process of viral infection." (PMID 41494040, 2026). "The rest of the viral infections did not undergo significant changes, which is more obviously different from the situation of most NbPirins, suggesting that different viruses may regulate Pirin gene expression through different mechanisms." (PMID 40004449, 2025).
lung adenocarcinoma (3 papers, 2021 to 2023). A carcinoma that arises from the lung and is characterized by the presence of malignant glandular epithelial cells. "A previous study has shown that piR-hsa-211106 inhibits the progression of lung adenocarcinoma and enhances chemotherapy sensitivity by pyruvate carboxylase." (PMID 36249068, 2022).
malaria (3 papers, 2009 to 2016). Malaria is a serious and sometimes fatal disease caused by a parasite that commonly infects a certain type of mosquito which feeds on humans. "While P. falciparum protein families are mostly unique to this specie, the conservation pattern of PYST and PIR support the co-existence of remodelling features common to rodent parasite in the case of PYST and rodent, simian and human malaria parasites in the case of PIR." (PMID 27503796, 2016). "An investigation into shared PIR proteins between liver and blood-stage parasites may hence provide valuable information for multi-stage malaria vaccine development." (PMID 25714922, 2015).
osteoporosis (3 papers, 2021 to 2023). A condition of reduced bone mass, with decreased cortical thickness and a decrease in the number and size of the trabeculae of cancellous bone (but normal chemical composition), resulting in increased fracture incidence. "Pirin is also associated to osteoporosis and NF-κB contributes to bone formation impairment in osteoporosis." (PMID 38033031, 2023). "In conclusion, our results indicated that piR-36741 had a protective effect on the osteogenic differentiation of BMSCs, and its overexpression could reduce bone loss in mice with osteoporosis." (PMID 34645714, 2021).
renal cell carcinoma (3 papers, 2022 to 2025). "Further filtration of these candidates based on read count in RNA‐seq and differential expression status in the Cancer Genome Atlas (TCGA) renal cell carcinoma cohort yielded 7 potential downstream targets of piR‐RCC." (PMID 40411401, 2025). "In conclusion, our study identifies piR‐RCC as a significant regulator that suppresses progression of renal cell cancer." (PMID 40411401, 2025). "The expression level of piR-823 was decreased in the tumor tissue of renal cell carcinoma but positively correlated with worse outcomes." (PMID 38060527, 2023).